AQP1 (aquaporin 1 (Colton blood group))
Diseases named in the same sentence as AQP1 in open-access papers (continued):
Sharing a sentence is not in itself a finding about the gene and the disease.
breast cancer (continued). "We will also discuss, below, how AQP1 is thought to be involved in estrogen mediated angiogenesis in the mammary gland and outline how increases in AQP3 expression promote FGF-2 stimulated migration of breast cancer cell lines." (PMID 24338153, 2014). "Previous studies have demonstrated elevated expression of AQPs (AQP1, 3 and 5) in breast cancer tissues relative to adjacent normal tissues." (PMID 23468877, 2013). "Previous studies suggested that AQP1 could facilitate cell migration in 4T1 breast cancer cells, and that AQP5 is required for proliferation and migration in MCF-7 breast cancer cells." (PMID 23468877, 2013). "In this review, we discuss the roles of AQP1, AQP3, AQP4, AQP5, and AQP7 in breast cancer progression and metastasis, including the role of AQPs in the tumor microenvironment, to highlight potential contributions of stromal-derived to epithelial-derived AQPs to breast cancer." (PMID 36212456, 2022). "Moreover, increased immunohistochemical expression of AQP1 in bioptic and surgical have been reported to predict improved overall survival (OS) in patients affected by mesothelioma, HER2-positive early breast cancer, colorectal cancer, and biliary tract carcinoma." (PMID 33807998, 2021). "We found that breast cancer patients with a high AQP1 expression could not benefit from CMF regimens." (PMID 32814878, 2021). "In the AQP1 high expression group, both OS and PFS (OS: P = 0.033, PFS: P = 0.001) of breast cancer patients treated with CEF regimens were significantly longer than those with non-CEF regimens, and patients with low AQP1 expression could not benefit from CEF regimens." (PMID 32814878, 2021). "In agreement, transcriptomic analyses from the Human Protein Atlas database showed distinctly higher levels for AQP1 and AQP3 transcripts, with AQPs 5, 7, 9 and 11 also showing possible moderately increased levels, as compared with overall median AQP levels in breast cancer biopsies." (PMID 32679804, 2020). "Moreover, in the AQP1 high expression group, PFS (P = 0.038) of breast cancer patients treated with CEF regimens was significantly longer than those treated with CMF regimens, and patients with the low AQP1 expression could not benefit from CEF regimens." (PMID 32814878, 2021).
colon carcinoma (43 papers, 2008 to 2025). "Genetic knockdown of AQP1 in melanoma and colon cancer cell lines was associated with reorganization of actin cytoskeleton, and decreased cell migration." (PMID 33499000, 2021). "In this study, microarray analyses of patients with stage II and III colon cancer showed that the expression of AQP1 is associated with lymph node metastasis, lymphatic vessels and vascular invasion." (PMID 32662230, 2020). "Jiang demonstrated reduced water permeability induced by AQP1 RNA-interference was associated with decelerated wound closure of HT-20 human colon cancer cell line." (PMID 31013775, 2019). "Jiang (2009) found that knocking down AQP1 was associated with re-localization of actin in migrating HT20 colon cancer cells, and a reduction in the activity of actin regulatory factors RhoA and Rac." (PMID 29922644, 2018). "Interestingly, the mechanisms of AQP1-induced cell migration and metastasis in colon cancer cells were found to be associated with actin protein re-localization and RhoA and Rac activation." (PMID 38336645, 2024). "AQP1, a Colton blood group antigen system gene, was reported to be associated with poor prognosis in colon cancer and lung adenocarcinoma, while seven of the fifteen genes were reported to be prognostic in one tumor type (GCNT2, FUT7, FUT3, FUT2, DARC, CR1 and BSG)." (PMID 35955933, 2022). "AQP1 appeared to be associated with higher risks of death in lung adenocarcinoma patients with a four-fold increase in hazard ratio (HR 4.0) and in pleural mesothelioma (HR 2.7), as well as breast, prostate and some colon cancers (HRs 2.6 to 3.4)." (PMID 32679804, 2020). "Yoshida used a tissue microarray to demonstrate that some AQPs, such as AQP1, may be associated with colon cancer invasion." (PMID 32662230, 2020). "Additionally, the expression of AQP1 has been reported to be associated with poor prognosis and other clinical characteristics such as histological grade and status of lympho-vascular invasion and nodal involvement in cervical carcinoma and colon cancer, etc." (PMID 35955933, 2022). "AQP1 molecular knockdown and inhibition dramatically reduced colon cancer cell migration, indicating that AQP1 is a promising target for the treatment of colon cancer." (PMID 38336645, 2024). "Previous studies demonstrated that pharmacological inhibition of AQP1 water and ion channels was an effective tool for limiting colon cancer cell motility measured in both wound closure assays and transwell invasion tests." (PMID 36831372, 2023). "Jiang’s work supports these findings, showing that altering AQP1 expression levels directly influences the migratory behavior of HT20 human colon cancer cells both in vitro and in vivo." (PMID 37762642, 2023). "In a previous study, ERCC1, PARP1, and AQP1 were identified as poor prognostic biomarkers for colon cancer at stages II-III." (PMID 37234985, 2023). "AQP1 is mainly expressed at the apical membrane of blood vessel endothelial cells and is upregulated in different carcinomas, including breast, lung, and colon carcinomas." (PMID 36389709, 2022). "Bacopaside II has been shown to activate autophagy by inhibiting G2/M cell cycle transition and inducing apoptosis of low and high AQP1-expressing colon cancer cells." (PMID 36061899, 2022). "The cation channel activity of AQP1 enhanced the migration of colon cancer cells, an effect blocked by the AQP1 ion channel inhibitors AqB007, AqB011, and 5-hydoxymethyl furfural." (PMID 35163313, 2022). "Pharmacological inhibition of AQP1 water channel activity in a colon cancer cell line impaired endothelial tube formation." (PMID 33499000, 2021). "Pharmacological inhibition of aquaporins slowed cancer cell migration; both ion conduction through the central pore of AQP1 and water flux through intrasubunit pores were necessary for maximal cell migration in an in vitro model of colon cancer." (PMID 33499000, 2021).
colon carcinoma (continued). "Bacopasides I and II isolated from the medicinal plant Bacopa have been identified as blockers of AQP1 channels, and shown to slow colon cancer cell migration." (PMID 34769339, 2021). "Bacopasides I and II from the medicinal plant Bacopa monnieri blocked colon cancer cell migration by targeting AQP1." (PMID 34769339, 2021). "For example, apoptosis was induced by pharmacological inhibition of AQP1 in colon cancer cells, and by siRNA knockdown of AQP1 in esophageal cancer cells." (PMID 33499000, 2021). "Our group has established a murine subcutaneous tumour model using moderately AQP1-expressing HT-29 colon cancer cells for evaluation of AQP1 modulators." (PMID 34066415, 2021). "Molecular knockdown and pharmacological inhibition of AQP1 in colon cancer cells significantly impaired migration, supporting AQP1 as a candidate target for colon cancer therapy." (PMID 32679804, 2020). "Colon cancer cells (HT20) transfected with AQP1 similarly exhibited increased cell migration rates and enhanced extravasation after injection via the tail vein in mice." (PMID 31477744, 2019). "Results here showed that combined administration of AQP1 water and ion channel blockers produced an amplified block of colon cancer cell migration in both colon cancer lines." (PMID 31477744, 2019). "In both cell lines, combined block of the AQP1 ion channel and water pores was more potent in impairing motility across colon cancer types than single agents alone." (PMID 31477744, 2019). "Results here are the first to demonstrate that combined block of the AQP1 ion channel and water pores is more potent in impairing motility across diverse classes of colon cancer cells than single agents alone." (PMID 31477744, 2019). "Our group previously reported that wound closure and invasion of moderately AQP1-expressing colon cancer cell line HT-29 was inhibited by AqB013." (PMID 31013775, 2019). "This work is the first to show the anti-invasive effects of AQP1 ion channel blocker AqB011 in colon cancer cells, suggesting a novel role for AQP1 ion conductance in facilitating cancer invasion." (PMID 31477744, 2019). "Results here are the first to show that AQP1 ion channel blocker AqB011 reduces colon cancer cell invasiveness in vitro, and to show that sensitivity to this agent depends on AQP1 localization in the plasma membrane." (PMID 31477744, 2019). "The differences in the dose response and AQP1 expression between the different colon cancer cell lines raises the possibility that the observed effects are influenced by the levels of AQP1 expression." (PMID 30037060, 2018). "Expression of AQP1 was determined by quantitative PCR and western immunoblot in the untreated colon cancer cell lines HT-29, HCT116, SW480, and SW620." (PMID 30037060, 2018). "This novel study investigated the anti-tumour effects of the AQP1 water channel inhibitor bacopaside II on colon cancer cell lines in vitro." (PMID 30037060, 2018). "Previously, we reported AQP1 over-expression in a proportion of patients’ colorectal cancer tumours compared to matched normal mucosa, with the highest AQP1 expression in the endothelial cells of the microvessels in colon tumour tissue." (PMID 29495367, 2018). "We also found that it significantly reduced migration of a colon cancer cell line expressing relatively high levels of AQP1." (PMID 29495367, 2018). "This was consistent with higher AQP1 expression in human umbilical vein endothelial cells (HUVECs) compared to colon cancer epithelial cell lines." (PMID 29495367, 2018). "When applied to AQP1-expressing HT29 colon cancer cells, these inhibitory compounds significantly reduced cancer cell motility, suggesting a physiological role of AQP1 ion conductance in cell migration." (PMID 29922644, 2018). "Two medicinal plant components, bacopaside I and bacopaside II from Bacopa monnieri, blocked AQP1 water channels and also inhibited the migration of AQP1-expressing colon cancer cells." (PMID 29099773, 2017).
colon carcinoma (continued). "An arylsulfonamide inhibitor of the AQP1 ion channel, AqB011, significantly impaired migration in the AQP1-expressing colon cancer cell line HT29." (PMID 29099773, 2017). "Our group previously demonstrated that AqB013 significantly reduces both migration and invasion properties of HT29 colon cancer cells which endogenously express AQP1, and suppresses endothelial tube formation of HUVECs in vitro." (PMID 28146084, 2017). "Expression of AQP1 in cell lines was assessed by quantitative (q) PCR, western blot and immunofluorescence, while expression of AQP1 in human colon tumour tissue was assessed by immunohistochemistry." (PMID 26912239, 2016). "Immunohistochemistry of colon tumour sections showed that AQP1 is expressed variably in the apical membrane and in the cytoplasm." (PMID 26912239, 2016). "Taken together these data suggest that the effect of AqB013 on impeding the migration of human colon cancer cells and endothelial cells expressing AQP1 is mediated by blocking the water channel activity of AQP1." (PMID 26912239, 2016). "The effect of varying concentrations of the AQP1 inhibitor AqB013 was tested on human colon cancer cell lines expressing high versus low levels of AQP1, using wound closure (migration) assays, matrigel invasion assays, and proliferation assays." (PMID 26912239, 2016). "Clinical evidence suggested that up-regulation of AQP1 was observed in a variety of malignancies such as brain tumors, cervical carcinoma, and colon tumors and high expression of AQP1 promoted tumor progression." (PMID 26812884, 2016). "AQP1 expression was correlated with the progression of colon cancer, including lymph node metastasis and lymphovascular invasion." (PMID 25886458, 2015). "The mechanism of AQP1-induced cells migration and metastasis in colon cancer cells was the relocalization of actin protein and activation of RhoA and Rac." (PMID 25886458, 2015). "AQP1 had the oncogenic property in colon cancer and was over-expressed in the early stage of the disease and through the late stage of colorectal carcinogenesis." (PMID 25886458, 2015). "AQP1 level is a poor prognostic factor for advanced colon cancer." (PMID 40989165, 2025). "Of note, AQP1 is also thought to be an ion channel, which is proposed to allow gated conduction of monovalent cations through the central tetrameric pore; this additional transporter activity from AQP1 may be important for colon cancer cell migration." (PMID 35847914, 2022). "Therefore, inhibition of the AQP1 water channel by AqB013 pharmacologically blocks the migration and invasion of colon cancer cells and can prevent the formation of endothelial cells in vitro." (PMID 32662230, 2020). "Alternatively, the role of AQP1 in colon cancer might depend on a dual water and ion channel function suggested to promote lamellipodial extension and cell migration." (PMID 32679804, 2020). "Western immunoblots demonstrated that unlike red blood cells (RBC) which had both monomeric (28 kDa) and glycosylated (30–40 kDa) forms, the predominant form observed in colon cancer cell lines was the 56 kDa dimer, consistent with previous reports describing AQP1 in RBC, HT-29, SW480 and HCT116." (PMID 30037060, 2018). "AQP1 is over-expressed in many human cancers including those of breast, colon and prostate and was shown to be a prognostic marker for poorer survival outcome in colon cancer patients." (PMID 29495367, 2018). "The dual water and ion conductance of AQP1 is essential for colon cancer cell migration in vitro." (PMID 29922644, 2018). "Together, these results provide further evidence that the observed effects of bacopaside II might be dependent on the levels of AQP1 expression in colon cancer cells." (PMID 30037060, 2018).
colon carcinoma (continued). "The association of AQP1 with RhoA and Rac has been previously suggested by Jiang who observed increase in the activation of these small G proteins in migrating HT20 colon cancer cells over-expressing AQP1, with more frequent polarised expression of actin at the cells’ leading edges." (PMID 28146084, 2017). "Furthermore, the AQP1 inhibitor AqB013 abrogated migration and invasiveness of colon cancer cells and prevented endothelial tube formation in vitro." (PMID 27409610, 2016). "Our hypothesis is that inhibition of AQP1 will reduce migration and invasiveness of colon cancer cells, and the migration and tube-forming capacity of endothelial cells in vitro." (PMID 26912239, 2016). "This study provides preliminary data showing that the AQP1 inhibitor AqB013 abrogates endothelial tube formation and reduces cancer cell migration and invasion and will be further investigated in an in vivo mouse xenotransplant model of human colon cancer." (PMID 26912239, 2016). "Hepatic cancer expresses similar types of AQPs with colon cancer, e.g. AQP1, AQP3, AQP5, and AQP9." (PMID 25886458, 2015). "AQP1 was thus proposed as an independent poor prognostic factor in colon cancer." (PMID 25886458, 2015). "Forced-expressed AQP1 in colon cancer cells increased the plasma membrane water permeability and migration ability, which could be inhibited by AQP1-specific blockers." (PMID 25886458, 2015). "This suggests that AQP1 may play a role in the early stages of colon cancer development." (PMID 37762642, 2023). "Therefore, AQP1 has been suggested as a possible therapeutic target for several tumors including tumors of the central nervous system as well as other solid tumors like melanoma or colon cancer." (PMID 33644043, 2021). "Higher levels of expression of peroxiporins AQP1, AQP3 and AQP5 in colon cancer cell lines correlated with better protection from oxidative insults, even when the background activity of antioxidant defense system components remained unchanged." (PMID 38451099, 2024). "During colorectal carcinogenesis, the expression of AQP1 and AQP5 was induced in early-stage disease (early dysplasia) and maintained through the late stages of colon cancer development." (PMID 35847914, 2022). "Therefore, AQP1 may be a promising biomarker for colon cancer prognosis." (PMID 32662230, 2020). "In studies of AQP1, AQP3 and AQP5 expression, some of these proteins were detected in colon cancer tissues and colorectal cancer cells, indicating that they play a role in colorectal cancer development." (PMID 32662230, 2020). "Combined pharmacological block of both the AQP1 water and ion channels in HT29 and SW480 colon cancer cells amplified the inhibition of 2D cell migration, as compared with effects of either inhibitor alone." (PMID 31477744, 2019). "This is consistent with our previous work showing that AQP1 activity and HT29 colon cancer cell migration were significantly blocked at concentrations that did not significantly reduce viability over 24 h." (PMID 29495367, 2018). "Moon and colleagues reported that AQP1 expression in colonic adenoma, primary and secondary colon carcinoma, but not in healthy colonic mucosa, is involved in the earliest stages of carcinogenesis." (PMID 38336645, 2024). "Specifically in the case of colon cancer, Moon and colleagues have shown that AQP1 is expressed in colonic adenoma and both primary and secondary colon cancer, but is absent in normal colonic mucosa." (PMID 37762642, 2023). "Bumetanide derivatives AqB007 and AqB011, which block the AQP1 nonselective cation channel in the central pore, reduced migration rates in colon cancer cell lines." (PMID 34769339, 2021). "AqB011 inhibits the human AQP1 ion current but not the water flux, and slows the migration of AQP1-expressing human colon cancer cells." (PMID 29755973, 2018).
colon carcinoma (continued). "In the case of colon cancer, Moon and colleagues showed expression of AQP1 in colonic adenoma, primary and secondary colon cancer, but not in normal colonic mucosa, suggesting a role of AQP1 in the early stage of colon cancer tumorigenesis." (PMID 28146084, 2017). "Third, the expression of AQP5, not AQP1, or AQP3, was found to be associated with Ras/ERK/Rb pathway activation in colon cancer cell lines and was linked with liver metastasis in colon cancer patients." (PMID 18478076, 2008). "On one hand, in our previous study, the ADCuh was found to be positively correlated with expression of AQP1 which had been demonstrated to be an independently negative prognostic factor for stage II/III colon cancer, in other words, higher AQP1 expression indicated worse survival." (PMID 37308941, 2023). "For instance, inhibition of AQP1 activity had no impact on the proliferation of the colon cancer cell line HT29, whereas a modest 17% reduction was observed in another colon cancer cell line, HCT-116." (PMID 37762642, 2023).